ABHD6 (abhydrolase domain containing 6, acylglycerol lipase)
Description:
Lipase that preferentially hydrolysis medium-chain saturated monoacylglycerols including 2-arachidonoylglycerol. Through 2-arachidonoylglycerol degradation may regulate endocannabinoid signaling pathways (By similarity). Also has a lysophosphatidyl lipase activity with a preference for lysophosphatidylglycerol among other lysophospholipids (By similarity). Also able to degrade bis(monoacylglycero)phosphate (BMP) and constitutes the major enzyme for BMP catabolism. BMP, also known as lysobisphosphatidic acid, is enriched in late endosomes and lysosomes and plays a key role in the formation of intraluminal vesicles and in lipid sorting.
Tractability: Small molecule: a structure with a bound ligand is known; a high-quality ligand is known. Antibody: its Gene Ontology location is reachable by antibodies, with high confidence; UniProt predicts a signal peptide or a membrane-spanning region. PROTAC: ubiquitination databases record sites on it; its protein half-life has been measured; a small molecule that binds it is known.
Target class: Enzyme; Hydrolase
Chemical probes: CHEMBL3613162, JZP 430, KT109 (high quality), KT195, KT203
Gene: Protein-coding gene on chromosome 3 (58,237,516 to 58,295,693, forward strand). Ensembl gene ENSG00000163686.
Subcellular location: Late endosome membrane; Lysosome membrane; Mitochondrion membrane
Subcellular location (Human Protein Atlas): Vesicles; Nucleoplasm
Pathways (Reactome):
Hemostasis: Arachidonate production from DAG
Gene Ontology:
Molecular function: monoacylglycerol lipase activity; protein binding; catalytic activity; phospholipase activity
Biological process: acylglycerol catabolic process; arachidonate metabolic process; lysobisphosphatidic acid metabolic process; monoacylglycerol catabolic process; negative regulation of cold-induced thermogenesis; phospholipid catabolic process; positive regulation of lipid biosynthetic process; regulation of retrograde trans-synaptic signaling by endocanabinoid
Cellular component: AMPA glutamate receptor complex; late endosome membrane; lysosomal membrane; membrane; mitochondrial membrane; plasma membrane; GABA-ergic synapse; glutamatergic synapse; mitochondrion; postsynaptic membrane
Genetic constraint (gnomAD): Loss-of-function variants: 29 observed, 37.07 expected, observed/expected ratio (o/e) 0.78, 90% interval 0.58 to 1.07. The upper end of that interval is the gene's LOEUF score, 1.07, which puts it in group 4 of 6, group 1 being the genes least tolerant of losing a copy. Missense variants: 370 observed, 431.84 expected, observed/expected ratio (o/e) 0.86, 90% interval 0.79 to 0.93. Synonymous variants: 145 observed, 168.59 expected, observed/expected ratio (o/e) 0.86, 90% interval 0.75 to 0.99.
Homologues: Orthologues: chimpanzee ABHD6 (99% identical), macaque ABHD6 (99% identical), rabbit ABHD6 (96% identical), guinea pig ABHD6 (95% identical), mouse Abhd6 (94% identical), rat Abhd6 (94% identical), dog ABHD6 (93% identical), pig ABHD6 (93% identical), tropical clawed frog abhd6 (76% identical), zebrafish abhd6a (69% identical), zebrafish abhd6b (66% identical), Drosophila melanogaster kraken (20% identical), and 1 more. Paralogues in human: EPHX2 (18% identical), EPHX4 (18% identical), SERHL2 (18% identical), ABHD11 (17% identical), EPHX3 (16% identical), ABHD5 (15% identical), ABHD4 (15% identical), ABHD8 (15% identical), MEST (14% identical), BPHL (14% identical), ABHD14A (13% identical), ABHD14B (11% identical).
Diseases named in the same sentence as ABHD6 in open-access papers:
ABHD6 is named in the same sentence as 46 diseases in open-access papers, as found by Europe PMC text mining. Sharing a sentence is not in itself a finding about the gene and the disease. The quoted sentences say what the papers report.
Obesity (11 papers, 2015 to 2026). Accumulation of substantial excess body fat. "The monoacylglycerol (MAG) hydrolase α/β-hydrolase domain-containing 6 (ABHD6) has been implicated in energy metabolism, with its global deletion conferring protection against obesity." (PMID 40886915, 2025). "Hence, pharmacological suppression of adipocyte ABHD6 could open new therapeutic avenues to treat obesity-associated metabolic diseases by enhancing energy expenditure." (PMID 33201859, 2020). "Here, we demonstrate that in insulin resistant women, ABHD6 mRNA expression is elevated in visceral fat and positively correlates with obesity and metabolic dysregulation." (PMID 40886915, 2025). "Nevertheless, the latest findings implicate ABHD6 in the development of different metabolic conditions, including MS, disorders in insulin secretion, obesity, and T2DM." (PMID 39286709, 2024). "Apparently, inhibition of ABHD6 in peripheral tissues counteracts obesity and co-morbidities, while ABHD6 inactivation in VMH neurons induces opposite effects." (PMID 36005632, 2022). "A selective knockdown of ABHD6 protects mice from high-fat-induced obesity, while PDHB on chromosome 13 has been described in cattle and pigs and is a candidate gene for intramuscular fat deposition." (PMID 32660013, 2020). "Subsequent studies revealed that the inactivation of ABHD6 protects against HFD-induced obesity, liver steatosis, and insulin resistance." (PMID 30894461, 2019). "Selective knockdown in liver and adipose tissue or pharmacological inhibition of ABHD6 protects mice from high-fat diet-induced obesity and hepatic steatosis." (PMID 26491015, 2015). "Very recent evidence implies that ABHD6 plays an important role in the development of obesity and liver steatosis." (PMID 26491015, 2015). "α/β Hydrolase domain-containing 6 (ABHD6) can act as monoacylglycerol hydrolase and is believed to play a role in endocannabinoid signaling as well as in the pathogenesis of obesity and liver steatosis." (PMID 26491015, 2015). "ABHD6 is elevated under conditions of diet-induced obesity and aging." (PMID 41727161, 2026). "Further, ABHD6 is tentatively annotated as a promiscuous lysophospholipase and shown to function as a general regulator of glycerophospholipid metabolism in the liver in mice models recapitulating high-fat diet–induced obesity." (PMID 39761854, 2025). "In summary, suppressing ABHD6 activity may hold promise for potential therapeutic applications in managing MS, obesity, and NAFLD." (PMID 39286709, 2024). "Therefore, both studies have proposed ABHD6 as a potential therapeutic target for obesity and type-2 diabetes." (PMID 34718828, 2021). "Also, we documented that whole-body ABHD6-KO mice are protected from diet-induced obesity, insulin resistance, and hepatic steatosis." (PMID 33201859, 2020). "Hence, adipocyte ABHD6 and MAG hydrolysis contribute to unhealthy WAT remodeling and expansion in obesity, and its suppression represents a candidate strategy to uncouple obesity from many of its immunometabolic complications." (PMID 40886915, 2025). "Antisense oligonucleotide (ASO)-mediated knock down of ABHD6 in murine liver and white adipose tissue of mice protected them from HFD-induced obesity, hepatic steatosis, and insulin resistance, suggesting a role of ABHD6 in the pathogenesis of metabolic syndrome." (PMID 36005632, 2022). "Thus, adipocyte ABHD6 suppression prevents most of the metabolic and inflammatory complications of obesity, but not obesity per se." (PMID 40886915, 2025). "As most studies utilizing ABHD6-KO animals are in the context of adipose tissue, insulin regulation, and obesity, we could not identify other CNS-specific model studies at the time of writing." (PMID 37958825, 2023).
Obesity (continued). "However, AAV-targeted ABHD6-KO and MAGL overexpression in the ventromedial hypothalamus has been shown to control the central signals that affect feeding responses and thermogenesis in a diet-induced obesity mouse model, thus establishing the neurological relevance of this model." (PMID 37958825, 2023). "However, the immunometabolic roles of adipocyte ABHD6 in WAT remodeling in response to nutri-stress and obesity are not known." (PMID 40886915, 2025).
Insulin resistance (6 papers, 2019 to 2026). Increased resistance towards insulin, that is, diminished effectiveness of insulin in reducing blood glucose levels. "We demonstrated that ABHD6 is an unidentified regulator of selective hepatic insulin resistance and contributes to MASLD and liver fibrosis." (PMID 41727161, 2026). "In contrast to the function of ABHD6 in the VMH, whole-body or peripheral ABHD6 loss-of-function is protective against DIO, insulin resistance, and hepatic steatosis; this is partly explained by enhanced energy expenditure, BAT activation, and WAT browning." (PMID 34718828, 2021). "Although studies of ABHD1 in diabetes and its complications are rare, research has found that inhibitors of ABHD6 in the same family may play a role in the treatment of type 2 diabetes, insulin resistance, and metabolic syndrome by promoting insulin secretion." (PMID 39619568, 2024). "Our study reveals an entirely different mechanism underlying selective hepatic insulin resistance that involves a previously unknown non-enzymatic function of ABHD6." (PMID 41727161, 2026). "Corroborating this, systematic administration of the ABHD6 inhibitor WWL70 also protected mice from DIO and insulin resistance and enhanced WAT browning, as observed in ABHD6-KO mice." (PMID 34718828, 2021).
metabolic syndrome (6 papers, 2019 to 2024). A cluster of metabolic risk factors for CARDIOVASCULAR DISEASES and TYPE 2 DIABETES MELLITUS. "ABHD6 is a lipase involved in endocannabinoid signaling and possibly has other effects in inflammation, metabolic syndromes, and insulin secretion." (PMID 35159112, 2022). "Pharmacological inhibition of ABHD6 causes beneficial metabolic effects in mice such as enhancement of insulin secretion and energy expenditure, thus qualifying ABHD6 as a promising target for the treatment of the metabolic syndrome and its comorbidities." (PMID 36005632, 2022). "The hydrolysis of MAG to FFA and glycerol is conducted by the MAG lipase (MAGL) in different tissues, although ABHD6, a MAG hydrolase, has also been implicated in the pathogenesis of metabolic syndrome, inflammation, and in cancer." (PMID 31349646, 2019). "Recent studies suggest that ABHD6 inhibitor have promising therapeutic efficacy in several preclinical mouse models of devastating diseases, such as metabolic syndrome, chronic inflammation, diabetes, including traumatic brain injury, multiple sclerosis, and epilepsy." (PMID 31849602, 2019).
Hepatic steatosis (5 papers, 2015 to 2025). Steatosis is a term used to denote lipid accumulation within hepatocytes. "Upon HFD feeding, ABHD6-deficient mice also exhibit reduced de novo lipogenesis in the liver that may counteract hepatic steatosis." (PMID 30894461, 2019). "In accordance with these data, our results showed reduced body weight and hepatic steatosis in ABHD6 KO mice fed the HFD." (PMID 30894461, 2019).
multiple sclerosis (5 papers, 2017 to 2021). A progressive autoimmune disorder affecting the central nervous system resulting in demyelination. "We have shown that inhibition of ABHD6 significantly reduces neuroinflammation and exerts neuroprotection in animal models of traumatic brain injury and multiple sclerosis." (PMID 29310667, 2018). "Studies from our lab and others have shown that ABHD6 inhibition has anti-inflammatory and neuroprotective effects in animal models of inflammation, traumatic brain injury, and multiple sclerosis by enhancement of cannabinoid signaling and reduction of eicosanoid signaling." (PMID 29310667, 2018). "Our recent studies have shown that a selective ABHD6 inhibitor WWL70 has anti-inflammatory and neuroprotective effects in animal models of traumatic brain injury and multiple sclerosis." (PMID 28086912, 2017). "ABHD6 participates in neurotransmission, inflammation, brain energy metabolism, tumorigenesis and other biological processes and is a potential therapeutic target for various neurological diseases, such as traumatic brain injury (TBI), multiple sclerosis (MS), epilepsy, mental illness, and pain." (PMID 34925039, 2021).
Ewing sarcoma (3 papers, 2018 to 2023). A small round cell tumor that lacks morphologic, immunohistochemical, and electron microscopic evidence of neuroectodermal differentiation. "For example, we observed elevated expression of ABHD6 in cell lines with a bone cancer origin, particularly those from Ewing’s sarcoma cell lines." (PMID 36760531, 2023). "Some patterns of expression were consistent across the two datasets, including high expression of ZDHHC3 and ABHD6 in bone cancer derived cell lines, particularly those derived from Ewing’s sarcoma tumors." (PMID 36760531, 2023). "The expression of ABHD6 varies between cancer types and is increased in Ewing sarcoma, prostate cancer, Burkitt lymphoma, and leukemia." (PMID 35159112, 2022). "Compared with the expression seen in normal tissues, the high expression of ABHD6 in the Ewing sarcoma family of tumours suggested that ABHD6 might be a potential diagnostic marker or drug target." (PMID 29794032, 2018).
depression (2 papers, 2016 to 2021). "In addition, the gene ABHD6, also differentially expressed between PTSD-TE, and involved in cannabinoid system signaling, is implicated in symptoms of anxiety and depression, which are highly likely to co-occur with PTSD." (PMID 33897478, 2021).
epilepsy (2 papers, 2019 to 2021). A brain disorder characterized by episodes of abnormally increased neuronal discharge resulting in transient episodes of sensory or motor neurological dysfunction, or psychic dysfunction. "Pharmacological inhibition of ABHD6 has an antiepileptic role in pentylenetetrazol-induced epilepsy and spontaneous epilepsy mouse models." (PMID 34925039, 2021). "In turn, ECS regulation by ABHD6 can affect the synaptic plasticity of neurons and play a role in CNS-injuring diseases such as epilepsy and brain injury." (PMID 34925039, 2021). "Studies have shown that ABHD6 blockers regulate activity-dependent 2-AG production and subsequent CB1R activation, which is characteristic of some forms of epilepsy." (PMID 34925039, 2021).
experimental autoimmune encephalomyelitis (2 papers, 2018 to 2021). An autoimmune demyelinating disease of the central nervous system that is produced experimentally in animals by the injection of homogenized brain or spinal cord in Freund's adjuvant. "In fact, in mouse models of experimental autoimmune encephalomyelitis and traumatic brain injury, ABHD6 inhibition reduces microglial reactivity and COX-2 expression." (PMID 34925039, 2021). "We have recently reported that systematic administration of WWL70 at 10 mg/kg significantly inhibits the activity of ABHD6 and elevates 2-AG levels in the experimental autoimmune encephalomyelitis (EAE) mouse brain and spinal cord." (PMID 29310667, 2018). "Based on the observation that WWL-70 plays a protective anti-inflammatory role in experimental autoimmune encephalomyelitis (EAE), blocking ABHD6 is considered to be a new strategy for the treatment of MS." (PMID 34925039, 2021).
lupus (2 papers, 2014 to 2022). "Of the remaining genes, ABHD6 has recently been suggested as the causal gene responsible for the association with lupus at this locus." (PMID 25620976, 2014). "While ABHD6 eQTLs were shown to correlate with lupus-association, there were also PXK eQTLs that were associated with lupus." (PMID 25620976, 2014). "A fourth, recent study included a moderately-powered fine mapping analysis of a European cohort and used expression quantitative trait locus analysis of nearby genes to argue for a role of ABHD6 in the increased lupus risk." (PMID 25620976, 2014). "Finally, ABHD6 gene expression was associated with an increased risk of systemic lupus erythematosus (SLE) in Europeans." (PMID 36005632, 2022).
neuroblastoma (2 papers, 2020 to 2026). Neuroblastoma (NB) is the most common solid, extracranial childhood tumor. "Interestingly, immunofluorescence analysis revealed that ABHD6 was predominantly localized in the nucleus in neuroblastoma cells." (PMID 41516358, 2026). "The pattern seen in the present study is similar to that seen in human SHSY5Y neuroblastoma cells, and in these cells, inhibition of ABHD6 but not MAGL per se reduces their ability to hydrolyse exogenously added 2-oleoylglycerol." (PMID 32286386, 2020).
Ataxia (1 paper, 2015). Ataxia refers to impaired coordination of voluntary muscle movement. "Similar to ABHD6, ABHD12 was originally described as a 2-AG-degrading enzyme, and mutations of ABHD12 cause the rare inherited disorder polyneuropathy, hearing loss, ataxia, retinitis pigmentosa, and early-onset cataract (PHARC)." (PMID 26491015, 2015).
autoimmune disease (1 paper, 2021). A disorder resulting from loss of function or tissue destruction of an organ or multiple organs, arising from humoral or cellular immune responses of the individual to their own tissue constituents. "ABHD6 is an important cell signaling regulator not only in the CNS but also in peripheral tissues, with an important role in the pathogenesis of many diseases, such as metabolic syndrome, obesity, and autoimmune diseases and cancer." (PMID 34925039, 2021). "Because hydrolysis of 2-AG leads to release of AA, the precursor of prostaglandins, ABHD6 may be related to the inflammatory process and autoimmune diseases." (PMID 34925039, 2021).
breast carcinoma (1 paper, 2026). "Spermine treatment induced a redistribution of ABHD6 toward the cytoplasm in breast cancer and colon carcinoma cells, as indicated by increased perinuclear signal and reduced nuclear staining compared with untreated cells (arrowheads d, e and f, respectively)." (PMID 41516358, 2026).
colon carcinoma (1 paper, 2026). "In contrast, ABHD6 localization was mainly cytoplasmic in the liver endothelial cell line SK-HEP-1 and, to a lesser extent, in the colon carcinoma cell line CT26 (arrowheads b and c, respectively)." (PMID 41516358, 2026).
Ewing family tumors (1 paper, 2021). "Abnormally high expression of ABHD6 is also observed in Ewing family tumors (EFTs) but not in other sarcomas, suggesting that it may be a new diagnostic target for these tumors." (PMID 34925039, 2021).
Headache (1 paper, 2023). Cephalgia, or pain sensed in various parts of the head, not confined to the area of distribution of any nerve. "Administration of ABHD6 and MAGL inhibitors significantly prevented and reduced CSD-induced periorbital allodynia, suggesting both a new strategy to treat headache pain and supporting prior reports with MAGL inhibitors in other headache models." (PMID 37287623, 2023).
liver fibrosis (1 paper, 2026). "This study opens an avenue for the development of a novel class of ABHD6 inhibitors to treat MASLD and liver fibrosis." (PMID 41727161, 2026).
melanoma (1 paper, 2025). A malignant, usually aggressive tumor composed of atypical, neoplastic melanocytes. "Intriguingly, CES1 was identified as the only 2-AG-hydrolyzing enzyme in this melanoma tissue, as MAGL and ABHD6/12 were not expressed." (PMID 39934865, 2025). "Unexpectedly, the most frequently expressed 2-AG-hydrolyzing enzymes MAGL, ABHD6, and ABHD12 were absent in melanoma and skin tissues." (PMID 39934865, 2025).
metastatic disease (1 paper, 2022). "However, pooled data of qPCR results and IHC signaling do support our conclusion that high ABHD6 expression is characteristic for late-onset metastatic disease in SF3B1mut UM." (PMID 35159112, 2022). "A high expression of ABHD6 is indicative of a long progression-free survival (PFS ≥ 60 months), whereas a low expression is indicative of early-onset metastatic disease (PFS < 60 months)." (PMID 35159112, 2022).
non-small cell lung carcinoma (1 paper, 2022). A group of at least three distinct histological types of lung cancer, including non-small cell squamous cell carcinoma, adenocarcinoma, and large cell carcinoma. "Evidence for a pro-oncogenic function of ABHD6 also came from a study investigating the role of ABHD6 in the pathogenesis of non-small cell lung carcinoma (NSCLC)." (PMID 36005632, 2022).